FOXO1 (forkhead box O1)
Diseases named in the same sentence as FOXO1 in open-access papers (continued):
Sharing a sentence is not in itself a finding about the gene and the disease.
tumor (continued). "Forkhead box O1 (FOXO1) belongs to a family of transcription factors known to have tumor suppressor roles in a wide variety of cancers." (PMID 33088284, 2020). "HDACIs not only potently inhibit the survival of myc-driven MB cells in vitro partly due to the upregulation of the FOXO1 tumor suppressor gene, but also synergize inhibition of tumor growth in vivo in combination with PI3KIs." (PMID 33147762, 2020). "A dramatically higher expression of CCL20 was detected in FOXO1(+) tumor cells, suggesting CCL20 was the downstream factor that was responsible for the recruitment of M2 macrophages." (PMID 33052231, 2020). "SKP2 can ubiquitinate and induce the degradation of the transcription factor FOXO1 which possesses a tumor suppressor function." (PMID 32226545, 2020). "In conclusion, our study showed that FOXO1 exerted anti-tumor effects in PCa through inhibition of cell proliferation and induction of cell cycle arrest." (PMID 32047567, 2020). "FoxO1, a member of the Fox family, is involved in apoptosis, stress, DNA damage, metabolism and etc Moreover, FoxO1 has been found to promote the carcinogenesis and tumour progression in a variety of tumours." (PMID 32057181, 2020). "Pathological assessment of the tumor tissues revealed that more CD68+ macrophages, especially CD206+ M2 macrophages, infiltrated the tumor stroma when tumor cells that highly expressed FOXO1 were in the marginal area." (PMID 33052231, 2020). "In the present study, we found that M2 macrophages were frequently located in the tumor-stroma region, where most of the tumor cells overexpressed FOXO1." (PMID 33052231, 2020). "The flow cytometry results showed that the percentage of M2 macrophages (CD163+/CD68+) was increased when M0 macrophages were co-cultured with FOXO1(+) tumor cells." (PMID 33052231, 2020). "In conclusion, this study firstly suggests that MBNL1‐AS1 acts as a tumor suppressor of BC by targeting miR‐135a/PHLPP2/FOXO1 axis, providing a novel insight for BC diagnosis and treatment." (PMID 31769229, 2020). "In our clinical cohort, we showed that FOXO1 was highly upregulated in tumor tissues compared to the adjacent non-tumor counterparts." (PMID 33052231, 2020). "In summary, our study shows that FoxO1 regulates anti-tumor effect (including phagocytosis) of macrophages through changing the metabolic hemostasis." (PMID 32973162, 2020). "A glutamate receptor antagonist, dizocilpine (also known as MK-801), has been shown to enhance FOXO1 nuclear localisation and promote its tumour suppressor function." (PMID 32372224, 2020). "The overexpression of FOXO1 in tumor cells indicated a high density of M2 macrophages in the tumor-stromal region and a worse prognosis in ESCC patients." (PMID 33052231, 2020). "ZBTB20 can act as a transcriptional repressor of FOXO1 to promote cell proliferation and tumor growth." (PMID 32375413, 2020). "Third, LINC00511 can accelerate tumor progression through regulating several tumor-associated signaling pathways such as RXRA/PLD1, PTEN/AKT/FOXO1, p38, ERK1/2 and JNK pathways." (PMID 32713253, 2020). "Western blotting, qRT-PCR, and enzyme-linked immunosorbent assay were used to evaluate chemokine ligand 20 (CCL20) and colony stimulating factor 1 (CSF-1) expression in FOXO1(+) and FOXO1(-) tumor cells." (PMID 33052231, 2020). "FOXO1 also inherently controls the anti-tumor immune response and the homeostasis and development of immune cells, including T cells, B cells, natural killer (NK) cells, macrophages, and dendritic cells." (PMID 33584800, 2020). "In malignancies, FoxO1 was shown to be an important tumor suppressor gene and was downregulated in many types of tumors." (PMID 32766159, 2020).
tumor (continued). "We show that overexpression of FOXO1 in tumor tissues from xenograft mouse decreased MALAT1 expression significantly." (PMID 32708561, 2020). "The importance of FOXO proteins in tumor suppression is further supported by the fact that the FOXO1, FOXO3a, and FOXO4 genes are all affected by chromosomal translocations detected in solid tumors and leukemia." (PMID 32704044, 2020). "Combining the powerful in vitro culture system and multi-omics analysis, we have drawn a connection between FoxO1, glycolysis, macrophages and phagocytosis of tumor cells." (PMID 32973162, 2020). "The implantation of a xenograft tumor also shows that FOXO1 downregulation promotes tumor growth, increases the microvessel area, and raises HIF-1α and VEGF levels." (PMID 32629884, 2020). "Generally, miR-182-5p regulates the apoptosis of tumor cells by targeting certain special genes, such as FOXO1, MTSS1, HMGA2, CASP9, and FOXO3, and these target genes were also predicted by our experiment." (PMID 32090086, 2020). "Probably because of its proteolysis effects on its substrates like p21, p27, PDCD4 and FOXO1, a large part of which are tumor suppressors, SKP2 mainly play oncogenic functions." (PMID 32226545, 2020). "At the same time, FoxO1 was reported to inhibit the metastasis process in prostate cancer cells and suppress tumor growth." (PMID 31906031, 2019). "The significance of miR-370 with TGFβ-RII and FOXO1 signaling pathways was also evaluated in other non-tumor conditions." (PMID 31231497, 2019). "The data showed that CB is a potent anti-tumor agent, and it further increased FOXO1-induced DDP chemosensitivity by antagonizing MYH9, which regulates GSK3β/β-catenin-mediated tumor stemness and EMT signals in NPC." (PMID 31754475, 2019). "Participation in the process of angiogenesis makes FoxO1 a crucial element of tumor growth and development." (PMID 31906031, 2019). "We demonstrate that FOXO1/MYH9 is a key suppressor of tumor stemness and EMT, thus inducing DPP chemosensitivity in NPC cells." (PMID 31754475, 2019). "The FOXO1 transcription factors are important regulators of cell cycle arrest and apoptosis, functioning as tumor suppressors." (PMID 31827405, 2019). "In the current study, we identified the lncRNA LINC01197 as a tumor suppressor and found that the FOXO1/LINC01197/β-catenin axis has tumor suppressor functions in PDAC." (PMID 31027497, 2019). "miR-96 can be considered as one of tumor-inducer and form competing endogenous RNA network with FOXO1 and DUSP1, which affects downstream EGFR signaling." (PMID 31579447, 2019). "FOXO1 represses GC growth and angiogenesis; inactivation of FOXO1 is associated with SIRT1 expression in human GC tissues and xenograft GC tumor tissues." (PMID 31689236, 2019). "Here, we demonstrate that FOXO1, which is directly targeted by miR-5188, suppresses Wnt/β-catenin and its downstream signals, tumor stemness, EMT and c-Jun, which reduced the CSC properties, metastasis, growth and chemoresistance of HCC." (PMID 31695788, 2019). "The effect of DR on reducing incidence of tumor was abolished in FoxO1 knockout heterozygous (HT) mice, indicating that FoxO1 is involved in the anti-tumor effects of DR." (PMID 31906091, 2019). "Five weeks after transplantation, tumor volume of mimics + Vector group was significantly higher than that of NC + Vector group (P < 0.01), and mimics + FOXO1 group had much smaller tumor volume when compared with mimics + Vector group (P < 0.01)." (PMID 30828264, 2019). "After 13 days of xenograft growth in vivo, significant decreases in HIF-1α, FoxO1, Sesn3, MnSOD and catalase expression were exhibited by the tumours from the 2ME + As2O3 treatment group compared with the tumours from the control group." (PMID 31905813, 2019). "Altogether, these results confirmed that FOXO1 suppresses tumor stemness and EMT signals by modulating the GSK3β/β-catenin pathway." (PMID 31754475, 2019).
tumor (continued). "Altogether, these data indicate that FOXO1 induces GSK3β to reduce β-catenin/TCF4-mediated tumor stemness and EMT signals." (PMID 31754475, 2019). "The functions of FoxO1 and its role in cancerogenesis and tumor progression are quite sophisticated and context-specific." (PMID 31906031, 2019). "Since our analysis of clinical specimens suggested a critical role for FOXO1 in tumorigenesis, we examined the role of FOXO1 in tumor cell growth (proliferation) and metastasis (migration) in functional studies." (PMID 31823759, 2019). "FOXO1/3 are tumor suppressors that induce the transcription of pro-apoptotic genes and death receptors involved in apoptosis, cell cycle regulation and DNA damage repair." (PMID 31366565, 2019). "We found that overexpressing MYH9 reversed the FOXO1-induced inhibition of NPC tumor stemness, migration, and invasion." (PMID 31754475, 2019). "The EWS-FLI1 gene regulates, though indirectly, the expression of FOXO1 which controls tumor growth and differentiation." (PMID 31275859, 2019). "Our studies demonstrated that CB potently induced FOXO1-mediated DDP sensitivity by antagonizing its binding partner MYH9 to modulate tumor stemness in NPC." (PMID 31754475, 2019). "ENT, a potent and selective Class I HDAC inhibitor, reduced the abundance of the tumor-driving PAX3:FOXO1 mRNA and protein expression." (PMID 31113472, 2019). "Here, we found that FOXO1 significantly inhibited NPC tumor stemness, migration, invasion, and metastasis in vitro and in vivo." (PMID 31754475, 2019). "Patient-matched tumor-normal pairs show 1.69-fold higher (P = 0.01; paired t-test) nuclear FOXO1 expression in UL, while the expression is as much as 2.32-fold greater (P = 1.52 × 10−9; Welch’s t-test) when all 335 UL are considered." (PMID 31649266, 2019). "In an orthotopic xenograft mouse model, methyl-imino selenium acid (MSA) was found to reactivate endogenous FOXO1, thereby significantly decreasing tumor growth." (PMID 31275859, 2019). "First, we observed that FOXO1 not only controlled tumor stemness and metastasis, but also sensitized NPC cells to cisplatin (DDP) in vitro and in vivo." (PMID 31754475, 2019). "In vivo studies also indicated that, FOXO1 inhibited tumor growth induced by miR-96 in nude mice and miR-96 promoted HCC progression through direct targeted inhibition of FOXO1." (PMID 30828264, 2019). "Factors included were age, FOXO1, clinical group, histology, nodal status, number of metastatic sites, primary site, sex, tumor size, and presence of metastases in bone/bone marrow, soft tissue, effusions, lung, distant lymph nodes, and other sites." (PMID 31456361, 2019). "Foxo1, a member of this family, is involved in T cell homeostasis and survival, and is considered as tumor suppressor in various cell systems." (PMID 29339772, 2018). "Possible explanations for differing expression status of FOXO1 in different tumor types include variable interactions with critical pathways depending on the spectrum of tissue type specific gene activation." (PMID 30478420, 2018). "The tumor expressed decreased levels of FOXO1 and RB1 as well as increased levels of oxidative stress markers, 8-hydroxy-2′-deoxyguanosine (8-OHdG) and 4-hydroxy-2-nonenal (4-HNE)." (PMID 28887603, 2018). "Taking together, we surmise that nimbolide induces CS in P-glycoprotein-overexpressing cells by targeting PTEN and modulating tumor cellular metabolic elements (HIF1α, FoxO1, c- MYC and ROS)." (PMID 30515268, 2018). "In our in vivo study, miRNA-370-3p plays a tumor-suppressive role, and this role is associated with the MGMT and FOXM1 downexpressions, while the expressions of TGFβ-RII and FOXO1 remain unchanged." (PMID 30497054, 2018).
tumor (continued). "As a tumor suppressor, FOXO1 negatively regulates the highly oncogenic phosphatidylinositol 3-kinase (P13K)/AKT signaling pathway." (PMID 30280037, 2018). "Two of them, miR-96 and miR-182, have been reported to target a tumor-suppressor gene of the Forkhead Box O subfamily of transcription factors 1 (FOXO1)." (PMID 29324832, 2018). "FOXO1 is thought to be a tumor suppressor that is down-regulated in HCC to exert its positive role in reversing the epithelial-to-mesenchymal transition program." (PMID 29707114, 2018). "Tumor volumes were significantly smaller in tumors of FOXO1-overexpressing A549 and H1299 cells compared to control cells." (PMID 30618730, 2018). "There are a further eight tumor-suppressor genes (DLEU2, CDKN2C, SPRY4, UBE2QL1, LIN9, TFPI2, LRIG3, DUSP1) and six genes serve as both oncogenes and tumor-suppressor genes (FOXO1, CAV1, KLF6, CDK6, PLK1, CTGF)." (PMID 30563222, 2018). "Western blot showed the differential expression of PTEN/AKT/FOXO1 pathway members in the tumor tissues of the two groups." (PMID 29867200, 2018). "For example, CDK1 is shown to be an inhibitor of FOXO1, which is known as a common tumor suppressor in different types of human cancer." (PMID 29861861, 2018). "Multivariate analysis including tumor stage, UICC stage and FOXO1 IHC demonstrated that tumor stage, UICC stage and FOXO1 IHC were independent prognostic markers (p = 0.0173, p < 0.0001, and p = 0.002)." (PMID 30478420, 2018). "Immunohistochemical staining result in FOXO1-overexpressing tumor tissues of mice showed decreased expression of c-JUN." (PMID 30618730, 2018). "FOXO1 plays a pivotal role in tumor suppression by inducing growth arrest and apoptosis, and is an important target in AKT signaling pathways." (PMID 27901487, 2017). "mRNA and protein analyses confirmed that YM155 downregulated the tumour promoters BIRC5 and ID1 and upregulated the tumour suppressors FOXO1 and CYLD." (PMID 28582447, 2017). "AKT has pleiotropic oncogenic functions that include inhibition of multiple tumor suppressors, such as FOXO1/FOXO3A, Bad, p27, and GSK3β, and promotion of other oncogenic pathways, such as mTOR, p70S6K1, Rac, and survivin." (PMID 29088759, 2017). "The mRNA expression of oncogenic proteins STAT3, IGF1, cyclin D2, and c-MYC increased with respect to increasing glucose concentrations while FOXO1 (tumor suppressor) showed decreased mRNA expression." (PMID 28114390, 2017). "aRMS is a highly aggressive tumor is characterized by the pathogenomic t(1:13) or t(2:13) translocation resulting in the chimeric gene-fusion product PAX3:FOXO1 or PAX7:FOXO1, respectively." (PMID 28968964, 2017). "Immunohistochemistry further confirmed that resveratrol reduced FoxO1 and FoxO3a staining in neoplasm foci." (PMID 28903430, 2017). "A dual-luciferase reporter assay system and chromatin immunoprecipitation further confirmed that FOXO1 suppresses tumor cell invasion and metastasis mainly through direct binding to the ZEB2 promoter." (PMID 27924058, 2017). "FOXO1 is a transcription factor that acts as a tumour suppressor, mediates cell cycle arrest and promotes apoptosis." (PMID 28582447, 2017). "Tumour volumes and growth rates were significantly decreased in tumours derived from FOXO1-overexpressing HONE1-EBV and SUNE1 cells." (PMID 27095304, 2016). "Immunohistochemistry for p‐AMPK and FOXO1 was carried out to confirm modulation of the AMPK–FOXO1 pathway in tumor xenografts." (PMID 27636742, 2016). "Cytosolic FoxO1 can bind to Atg7 to induce autophagy in human tumour cells independently of its transcriptional activity." (PMID 27010363, 2016). "This was also confirmed by immunohistochemistry of FOXO1-overexpressing tumour tissues derived from NPC mouse models." (PMID 27095304, 2016). "Restoration of FoxO1 expression partially slowed down tumor growth of ZBTB20 overexpressing SMMC-7721 cells (P < 0.01)." (PMID 26893361, 2016).
tumor (continued). "AKT also phosphorylates the pro-apoptotic and anti-proliferative transcription factor FOXO1, which leads to its exclusion from the nucleus and cytosolic degradation, thereby connecting tumor cell metabolism with cell cycle progression and survival." (PMID 26878387, 2016). "The exposure of U87 cells to S109 resulted in an increased nuclear accumulation of key tumor-suppressor proteins (Foxo1, p21, and p27) compared with the control." (PMID 27733172, 2016). "Bioinformatics analysis indicated that the tumor suppressor FOXO1 is a theoretical target gene of miR-135a." (PMID 27486383, 2016). "JNK activation correlated with a longer patients survival (P =0.008) and patients with a JNK-active and FOXO1-inactive tumor had a higher survival rate than the remainder of the population (P = 0.004)." (PMID 27268017, 2016). "Our studies demonstrate that as a tumour suppressor, miR-3188 directly targets mTOR to stimulate its own expression and participates in FOXO1-mediated repression of cell growth, tumorigenesis and NPC chemotherapy resistance." (PMID 27095304, 2016). "The expression of FOXO1 and its downstream anti-oxidative stress enzymes such as catalase and MnSOD were also at a high level in tumor tissues." (PMID 27566573, 2016). "FOXO1 which is a member of the forkhead transcriptional factor family, functions as a tumor suppressor in various carcinomas." (PMID 27486383, 2016). "Although the tumour suppressive activity of FOXO1 has been well characterized for some cancers, little is known of its function and molecular mechanisms in NPC." (PMID 27095304, 2016). "In this study, we identified the tumor suppressor - FoxO1 as a direct downstream target of miR-9 based on the luciferase reporter assay, which is in concomitant with that miR-9 is oncogenic in NSCLCs." (PMID 26593208, 2015). "The upregulation of FOXO1 during osteoblast differentiation and its downregulation in OS suggest a tumor suppressor activity of this gene in OS tumorigenesis." (PMID 26344693, 2015). "In various model systems, FOXO1 acts as a tumor suppressor by multiple mechanisms including regulating expression of target genes involved in control of cell-cycle progression and apoptosis." (PMID 26344693, 2015). "In agreement, the miRNA antagonist antagomir-3127 suppressed HCC cell proliferation and tumor growth by inhibiting the AKT/FOXO1 signaling." (PMID 25849943, 2015). "In conclusion, our data provide evidence supporting the tumor-suppressing roles played by FOXO1 in OS tumorigenesis." (PMID 26344693, 2015). "Single deletion of either Foxo1, Foxo3, or Foxo4 genes resulted in minor alterations in the incidence of neoplasms and lifespan; only triple knockout of Foxo1, Foxo3, and Foxo4 genes caused the cancer-prone phenotype and shortened lifespan." (PMID 25808402, 2015). "Decline of phosphorylation of FOXO1 and FOXO3a caused by CAPE treatment elevates their tumor suppressor activity." (PMID 25984601, 2015). "It has been shown that the transcription factor FOXO1 acts as a tumor suppresser, and can be phosphorylated by Akt and SGK1 protein kinases." (PMID 25749387, 2015). "FOXO1 is a transcription factor for p27, p21, FasL, and Bim, which function as tumor suppressors by blocking the G1/S transition and inducing apoptosis." (PMID 25909227, 2015). "Of a range of cellular functions, FOXOs have been shown to act as tumor suppressors, and, in fact, FOXO1, FOXO3 and FOXO4 show redundancy for this function." (PMID 25806826, 2015). "To conclude, our results proved FOXO1 as a tumor suppressor in OS at least partially by suppression of the Wnt/β-catenin pathway." (PMID 26344693, 2015). "FOXO1 acts as tumor suppressor and its inactivation has been documented in many types of human cancer." (PMID 25749387, 2015). "When murine and human tumor cultures were treated with 2 μM entinostat for 72 h, a pronounced reduction in Pax3:Foxo1 protein levels was observed." (PMID 25030697, 2014).